BRCA1 (BRCA1 DNA repair associated)
Diseases named in the same sentence as BRCA1 in open-access papers (continued):
Sharing a sentence is not in itself a finding about the gene and the disease.
ovarian carcinoma (continued). "Findings from an international observational study of 19,581 BRCA1 and 11,900 BRCA2 carriers from 55 centers in 33 countries on 6 continents provide strong evidence that breast and ovarian cancer risks vary by type and location of BRCA1/2 mutation." (PMID 27242959, 2016). "We report a comprehensive analysis of the prevalence of BRCA1 and BRCA2 germline mutations in Pakistani patients with TNBC and non-TNBC selected for age of onset or family history of breast/ovarian cancer." (PMID 27553291, 2016). "Mutations in the BRCA1, BRCA2 and PALB2 genes are well-established risk factors for the development of breast and/or ovarian cancer." (PMID 26843898, 2016). "Regulatory approval of olaparib for the treatment of advanced ovarian cancer is based on results of a nonrandomized phase II trial of 298 patients with solid tumors and germline BRCA1 or BRCA2 mutations, including 193 patients with recurrent ovarian cancer." (PMID 27983698, 2016). "Although germline mutations in the tumor suppressor BRCA1 and BRCA2 genes are associated with a high risk of breast and ovarian cancer, however, they have also been shown to correlate with other cancers, including gastric cancer." (PMID 26779294, 2016). "This makes PARP1 an interesting therapeutic target in the context of malignancies with deficient HR, such as BRCA1 and BRCA2 mutant breast and ovarian cancers." (PMID 27336789, 2016). "Five BRCA1 and 3 BRCA2 recurrent mutations account for more than half of the patients with proven hereditary breast/ovarian cancer originating from FVG and neighboring geographic areas." (PMID 26852130, 2016). "For example, methylation of the BRCA1 promoter has been shown to transcriptionally silence BRCA1 leading to lower levels of BRCA1 messenger RNA (mRNA), which correlates with disease characteristics of breast and ovarian cancers." (PMID 27788678, 2016). "Several studies have reported somatic BRCA1 and BRCA2 mutations in a considerable proportion of breast and ovarian cancers." (PMID 27533253, 2016). "Carrying an inherited mutation in the BRCA1 or BRCA2 genes increases a woman's lifetime risk of developing breast and ovarian cancers although there are considerable differences in disease manifestation." (PMID 27015555, 2016). "BRCA1 and BRCA2 screening for mutations was carried out on 1114 breast and/or ovarian cancer patients complying with the eligibility criteria for BRCA testing." (PMID 26852130, 2016). "IGF1R expression level is raised in non-BRCA1-mutated ovarian cancer cells compared with normal tissue and additionally IGF1R levels are significantly increased in BRCA1-inactivation ovarian cancer." (PMID 27405474, 2016). "Carriers of BRCA1 and BRCA2 germ-line mutations usually develop breast and/or ovarian cancers, however there is also some association with other cancer types." (PMID 27555886, 2016). "Ovarian cancer was present in 6/10 families with the BRCA1 c.676delT (1 to 5 patients per family) and in 4/18 families with the BRCA2 c.7806-2A > G (1 to 3 patients per family)." (PMID 26852130, 2016). "The BRCA1 and BRCA2 tumour suppressor genes are the most important predisposition genes for ovarian cancer and account for about 90 % of ovarian cancers in the hereditary breast and ovarian cancer syndrome." (PMID 26560874, 2016). "The elevated expression of haemoxygenase, which is an Nrf1/2 dependent gene, as a result of PB treatment in BRCA1 blocked BG1 ovarian cancer cell has also been reported earlier by our own group, confirming the activation of the antioxidant mechanism." (PMID 27220670, 2016). "Other personal and familial history was notable for breast and ovarian cancer in both BRCA1 and BRCA2 patients." (PMID 27069714, 2016). "Both BRCA1/BRCA1a K109R and disease associated C61G mutants, which are localized mainly in the cytoplasm, fail to suppress the growth of TNBC and ovarian cancer cells." (PMID 28164176, 2016).
ovarian carcinoma (continued). "We analyzed somatic BRCA1 status in hereditary ovarian cancers undergoing short-term preoperative therapy (on average, 3 cycles of platinum-containing cocktails given with 21-day intervals)." (PMID 27555886, 2016). "In 13 studies containing at least 60 families in which one or more cases of ovarian cancer were ascertained, the frequency of BRCA1 ranged from 24.2 to 76.2 % and the frequency of BRCA2 ranged from 1.0 to 16.7 %." (PMID 27004793, 2016). "The multiple steps of damage signaling also involve BRCA1, well known for its involvement in breast and ovarian cancers." (PMID 27802335, 2016). "The largest and most recent meta-analysis demonstrated that BRCA1 and BRCA2 mutations have positive prognostic effects on ovarian cancer overall and progression-free survival." (PMID 27004793, 2016). "The recommendation to pursue BRCA1/2 testing is based on patient’s family history of breast/ovarian cancer, age of disease-onset and/or pathologic parameters of breast tumors." (PMID 27553291, 2016). "While hereditary breast and ovarian cancer has been a common indication for germ-line genetic evaluation since BRCA1 and BRCA2 were identified, many additional genes have subsequently been implicated in hereditary cancer." (PMID 26681312, 2016). "A recent study demonstrated that both germline (inherited) and somatic (acquired) loss-of-function mutations in BRCA1 and BRCA2 genes predict higher rates of platinum sensitivity and better overall survival (OS) in primary ovarian carcinoma." (PMID 28003870, 2016). "Taken together, germline and somatic testing for BRCA1/2 provides important information for patients with ovarian cancer and this knowledge can directly impact clinical care." (PMID 27242959, 2016). "In ovarian cancer samples, BRCA1-IRIS expression increases with tumor progression together with survivin." (PMID 27489859, 2016). "BRCA1/BRCA2 mutations are often found in hereditary breast and ovarian cancers, while somatic mutations of BRCA1/BRCA2 are rare in sporadic breast and ovarian cancers." (PMID 26967246, 2016). "In summary, in this study we demonstrated that SOX2 overexpression occurs in a fraction of women with BRCA1 and BRCA2 mutations prior to ovarian cancer initiation and in the majority of patients with HGSOCs irrespective of tumor stage." (PMID 27492892, 2016). "Our results demonstrated that the frequency of BRCA1 and BRCA2 mutations among Chinese women with familial breast/ovarian cancer was 23.3 %." (PMID 26852015, 2016). "Mutations in DNA damage response factors BRCA1 and BRCA2 confer sensitivity to poly(ADP-ribose) polymerase (PARP) inhibitors in breast and ovarian cancers." (PMID 27613518, 2016). "Our study suggested that BRCA1 and BRCA2 mutations accounted for a considerable proportion of the hereditary breast/ovarian cancer patients in eastern China and that the spectrum of the mutations in these genes exhibited unique features." (PMID 26852015, 2016). "Studies from our group have earlier shown that Plumbagin can target BRCA1-defective breast (unpublished data) as well as ovarian cancers more effectively than it can target BRCA1-competent cells from both cancers." (PMID 27229859, 2016). "The role of germline mutations in BRCA1 and BRCA2 genes in the risk of the development of ovarian cancer is clinically well established." (PMID 26753012, 2016). "In young women identified with a BRCA1 or BRCA2 mutation, RRS is performed in an effort to reduce ovarian cancer risk while maintaining adequate hormonal levels to avoid the effects of early menopause." (PMID 27200296, 2016). "The effect of this peptide was even seen in combination treatment with cisplatin, suggesting an in vivo sensitization of ovarian cancer cells to cisplatin by inhibiting BRCA1- IRIS survival pathways." (PMID 27489859, 2016). "Germline mutations in BRCA1 and BRCA2 are the most penetrating genetic predispositions for breast and ovarian cancer, and their presence is largely ethnic-specific." (PMID 26848529, 2016).
ovarian carcinoma (continued). "Mutations in HR genes such as BRCA1, BRCA2, or RAD51C predispose individuals to breast and ovarian cancers." (PMID 26748828, 2016). "Germline mutations in breast and ovarian cancer susceptibility genes, BRCA1 and BRCA2, significantly increase lifetime risk of developing ovarian cancer compared to the general population." (PMID 27588493, 2016). "We examined the entire coding sequences of the BRCA1 and BRCA2 genes and genotyped a recurrent mutation of the PALB2 gene (c.509_510delGA) in 121 women with familial and/or early-onset breast or ovarian cancer from Southern Poland." (PMID 26843898, 2016). "The BRCA1 mutation-positive MBC patient was <40 years old at diagnosis and had a first-degree family history of breast and ovarian cancer." (PMID 27377827, 2016). "In this review, we focus on the Rad52 activities and functions in HR and the possibility of using human RAD52 as therapeutic target in BRCA1 and BRCA2-deficient familial breast cancer and ovarian cancer." (PMID 27649245, 2016). "Monoallelic germline mutations in the tumour suppressor genes BRCA1 and BRCA2 predispose women to breast and ovarian cancer." (PMID 27037238, 2016). "In our study, the age at the onset of ovarian cancer for BRCA1 wild type was almost 10 years postponed than in carriers of BRCA1 mutations (median 56 years vs 47 years, respectively, p = 0.004)." (PMID 26753012, 2016). "BRCA1 and BRCA2 germline mutations are the most frequent HBOC signatures, and they increase the lifetime risk of developing breast and ovarian cancers by as much as 80%." (PMID 28009814, 2016). "The potential for relatives to make an informed decision to seek their own diagnostic quality BRCA1/2 test and subsequent follow-up (e.g., seek risk-reducing surgery) may arguably be considered a significant benefit of returning BRCA1/2 information to patients who already have ovarian cancer." (PMID 27769273, 2016). "Gastric cancer (GC) is part of the spectrum of diseases linked to BRCA1 and BRCA2 mutations that increase the risk of breast and ovarian cancer." (PMID 26779294, 2016). "Taken together, these results indicate that in both BRCA1 and BRCA2 mutation carriers there is only one peak of association with ovarian cancer risk at 9p22." (PMID 27463617, 2016). "The PARP inhibitor Olaparib [AZD2281] has been approved by the FDA for use in pretreated ovarian cancer patients with defective BRCA1/2 genes, and by the EMEA for maintenance therapy in platinum sensitive ovarian cancer patients with defective BRCA1/2 genes." (PMID 27884198, 2016). "Worldwide, give the high incidence of ovarian cancer, the opportunity to identify BRCA1/2 carriers at the time of their cancer diagnosis – and those at risk for developing disease – can impact therapeutic interventions." (PMID 27242959, 2016). "Germline mutations in BRCA1 and BRCA2, involved in HR and FA repair, increase the risk of developing breast and ovarian cancer 40-80% and 11-40%, respectively, in addition to other cancer types." (PMID 27004405, 2016). "Germline mutations in the BRCA1 and BRCA2 genes are the most important causes of hereditary breast and ovarian cancer." (PMID 26967246, 2016). "We compared the frequency and spectrum of BRCA1 and BRCA2 mutations contributing to breast and ovarian cancer families in Malopolska with those that have been previously reported in Polish families." (PMID 26843898, 2016). "The most common and aggressive histotype of epithelial ovarian cancer (EOC), high grade serous carcinoma (HGSOC) is associated with germ line BRCA1 mutations with a lifetime risk of 40–60%." (PMID 28164176, 2016). "There are only a few studies that have analyzed the frequency of BRCA1/BRCA2 mutations in fallopian tube and peritoneal cancer independently of ovarian cancer." (PMID 27532258, 2016). "Overcoming innate olaparib resistance in ovarian cancer cells with WT BRCA1 or 2 is potentially valuable clinically." (PMID 26959114, 2016).
ovarian carcinoma (continued). "Olaparib received accelerated approval from the Food and Drug Administration (FDA) for the use in patients with BRCA1/2-driven ovarian cancers who received at least 3 prior lines of chemotherapy." (PMID 27555886, 2016). "These inhibitors have fewer side effects and are used to treat aggressive cancers, such as cancers involving hereditary BRCA1/2 and triple negative breast and ovarian cancer." (PMID 26973813, 2016). "An exploratory pharmacogenetic analysis was conducted in the international ovarian cancer phase III trial, AGO-OVAR 16, which found that patients with clinically important germ-line BRCA1/2 mutations had improved progression-free survival prognosis." (PMID 27769273, 2016). "Herein we reported five novel pathogenic BRCA1/2 mutations and six novel VUS with pathogenic potential in patients with ovarian cancer." (PMID 27907908, 2016). "Early phase clinical trials with PARPi have been promising in patients with advanced BRCA1 or BRCA2-associated breast, ovary and prostate cancer and have led to limited approval for treatment of BRCA-deficient ovary cancer." (PMID 27428646, 2016). "Bilateral salpingo-oophorectomy should be offered to women with a BRCA1 or BRCA2 mutation, between 35 and 40 years and after completion of childbearing, or individualise based on the earliest age of ovarian cancer diagnosed in the family." (PMID 26669313, 2015). "Inhibition of PARPs is a promising strategy for targeting cancers with defective DNA-damage repair, including BRCA1 and BRCA2 mutation-associated breast and ovarian cancers." (PMID 26268938, 2015). "Low protein expression of BRCA1 is known to promote breast- and ovarian cancers and FBXO44 promotes ubiquitination and degradation of BRCA1." (PMID 25970626, 2015). "It is well established that germline mutations in BRCA1 and BRCA2 confer susceptibility to breast and ovarian cancers." (PMID 26622941, 2015). "Bilateral salpingo-oophorectomy should be offered to women with a BRCA1 or BRCA2 mutation, between 35 and 40 years and after completion of childbearing, or individualised based on the earliest age of ovarian cancer diagnosed in the family (II,A)." (PMID 26669313, 2015). "Women who inherit a deleterious BRCA1 or BRCA2 mutation have upto a 40% and 20% lifetime risk, respectively, ofdeveloping ovarian cancer, and higher risks of developing breast cancer." (PMID 26669452, 2015). "Ovarian cancer is also a hormone-dependent malignancy, so the role of PGR gene in BRCA1+ and BRCA1- ovarian cancers can be different as well." (PMID 25591549, 2015). "We investigated the immunohistochemical expression of DBC1 and BRCA1 and their prognostic significance in 104 ovarian carcinomas." (PMID 25823848, 2015). "When mutations in BRCA1, BRCA2, or other cancer-susceptibility genes have been identified, patients with ovarian carcinoma can be treated with new, innovative therapies." (PMID 26109557, 2015). "Positive expression of DBC1 and BRCA1 were seen in 63% (66/104) and 44% (46/104) of overall ovarian carcinomas, respectively." (PMID 25823848, 2015). "The high incidence of germline BRCA1 and BRCA2 mutations in ovarian cancer, has suggested that genetic assessment of women with ovarian cancer especially those with nonmucinous high-grade serous histology, will improve mutation carrier detection rates." (PMID 25884701, 2015). "CCNE1 amplification/overexpression is mutually exclusive to BRCA1 deletion/underexpression in ovarian cancers (p-value = 0.073)." (PMID 26427375, 2015). "The majority of mutations found to date in the BRCA1/BRCA2 genes in breast and/or ovarian cancer families are point mutations or small insertions and deletions scattered over the coding sequence and splice junctions." (PMID 25632310, 2015). "Tumor suppressor genes BRCA1 and BRCA2 are the two main breast and ovarian cancer susceptibility genes, and their genetic testing has been used to evaluate the risk of hereditary breast and ovarian cancer (HBOC)." (PMID 25802882, 2015).
ovarian carcinoma (continued). "In a recent meta-analysis of case–control studies in BRCA1 and BRCA2 mutation carriers, a significant 50 % risk reduction of ovarian cancer was associated with the past use of combined oral contraceptives." (PMID 26669313, 2015). "BRCA1 expression was significantly associated with OS and RFS in 104 ovarian carcinomas (OS; P = 0.005, RFS; P = 0.002) and 75 serous carcinomas (OS; P = 0.047, RFS; P = 0.038) by univariate analysis." (PMID 25823848, 2015). "Sister was diagnosed with BRCA1 positive ovarian cancer, and a brother with squamous cell carcinoma of the tongue." (PMID 26429871, 2015). "Olaparib has demonstrated single agent activity in breast and ovarian cancer patients with BRCA1/2 germline mutations, with over 40% response rate reported in patients with BRCA1-mutant ovarian cancer." (PMID 25868852, 2015). "Overall, BRCA1 and BRCA2 mutation carrier frequencies of 13-15% have been reported for ovarian cancer patients from the general population." (PMID 25884701, 2015). "In conclusion, the current standard RRSO at age 35–40 (BRCA1) or 40–45 (BRCA2) is highly effective in reducing ovarian cancer incidence." (PMID 26286255, 2015). "The association of germline mutations in the breast cancer susceptibility gene 1 (BRCA1) and the breast cancer susceptibility gene 2 (BRCA2) with the development of breast and ovarian cancers have been widely researched and recognised." (PMID 26236408, 2015). "We investigated the clinical implications of the loss of XCI in ovarian cancer and the association between the loss of XCI and BRCA1 dysfunction." (PMID 25742136, 2015). "Based on the inhibitory role of DBC1 for the BRCA1, the co-expressing pattern of these two molecules in the poor prognostic group of ovarian carcinomas is questionable and paradoxical as BRCA1/2 defective cancers are more susceptible to therapy." (PMID 25823848, 2015). "The most important predisposition genes BRCA1 and BRCA2, conferring high life-time risks of breast and ovarian cancer, are involved in the homologous recombination repair (HRR) of DNA double-strand breaks (DSB)." (PMID 25918678, 2015). "The 218 wild-type BRCA1/2 ovarian cancers were randomly assigned to a training set (n=109) and a testing set (n=109)." (PMID 25537514, 2015). "When cultured with various concentrations of RB, both a BRCA1 mutation cell line, UWB, and wild-type BRCA1 expressing ovarian cancer cells showed dose-dependent growth suppression." (PMID 26618054, 2015). "Inheritance of a deleterious mutation in either of the BRCA1 or BRCA2 genes greatly increases a woman's lifetime risk of developing breast and ovarian cancers." (PMID 26246475, 2015). "We compare the standard strategy to reduce ovarian cancer risk, i.e. RRSO at recommended age of 35–40 in BRCA1 and at recommended age of 40–45 in BRCA2 mutation carriers, with an innovative risk-reducing strategy." (PMID 26286255, 2015). "Germline mutations in BRCA1 and BRCA2 genes are the most frequent cause of strong genetic predisposition to breast and ovarian cancer." (PMID 26163143, 2015). "In our study, the expression of DBC1 and BRCA1 showed positive correlation and the expressions of both molecules was related with platinum-resistance and shorter survival of ovarian carcinoma patients." (PMID 25823848, 2015). "The frequency of BRCA1 and BRCA2 mutations in ovarian cancer patients varies depending on histological subtype and population investigated." (PMID 25884701, 2015). "There were 31 women, 21 BRCA1 and 10 BRCA2 mutation carriers, with a previous diagnosis of ovarian cancer, and four of them (2 BRCA1 and 2 BRCA2 mutation carriers) subsequently developed a breast tumor." (PMID 26163143, 2015). "Inactivating mutations in the BRCA1 (MIM 113705) and BRCA2 (MIM 600185) genes confer a high risk of developing breast and ovarian cancer." (PMID 25683334, 2015).